ASS1P6 (argininosuccinate synthetase 1 pseudogene 6)
Synonyms: ASSP6
Gene: Processed pseudogene on chromosome Y (11,922,536 to 11,923,769, reverse strand). Ensembl gene ENSG00000215583.
Diseases named in the same sentence as ASS1P6 in open-access papers:
ASS1P6 is named in the same sentence as 1 disease in open-access papers, as found by Europe PMC text mining. Sharing a sentence is not in itself a finding about the gene and the disease.
ASS1P6 shares sentences with these, for which no sentence is quoted: Azoospermia (1 paper).